IRF4 (interferon regulatory factor 4)
Diseases named in the same sentence as IRF4 in open-access papers (continued):
Sharing a sentence is not in itself a finding about the gene and the disease.
infection (continued). "For CD8+ T cells, Irf4 deletion after recovery of infection completely prevented expansion of the memory T cell population following re-infection and it is very likely that this holds true for secondary responses of Th17 and Th2 cells as well." (PMID 37469513, 2023). "In contrast to Th17 cells, IFN-γ+ and TNF-α+ CD4+ Th1 cells were present in roughly similar frequencies in spleen and colon of Irf4+/+ and Irf4-/- mice under steady state conditions as well as following infection." (PMID 37469513, 2023). "Here we use mouse infection models for Citrobacter rodentium and Strongyloides ratti to analyze the function of IRF4 in T helper (Th) 17 and Th2 cell responses, respectively." (PMID 37469513, 2023). "Th17 cell populations strongly increased in both spleen and colon following infection of Irf4+/+ and Irf4+/- mice." (PMID 37469513, 2023). "After day 28, all Irf4+/+ and Irf4+/- mice had stopped shedding of S. ratti L1 and eggs, indicating clearance of infection." (PMID 37469513, 2023). "In contrast, Irf4-/- mice showed more extensive shedding at the maximum of infection and although shedding subsequently declined, S. ratti-DNA was still detected in feces after 11 weeks." (PMID 37469513, 2023). "Our results showed that infection of Blau-KI BMDCs with an IRF4-expressing lentivirus restored the expression of IRF4." (PMID 36189261, 2022). "Overall, scRNA-seq data confirm that T2 LCLs are much more likely to enter fully lytic infection than T1 LCLs, and suggest that both viral and cellular factors (including NFATc1, IRF4 and EBF1 levels) contribute to this difference." (PMID 35472072, 2022). "After STM infection migratory ILCs express significantly higher levels of Ccl3, Gbp2, Gbp6, Irf1, Irf4, Irf7, Pml and Stat1, all of which are regulated in response to interferon gamma." (PMID 33414524, 2021). "The role for IRF4 was further shown in mouse models of infection in which ITK signaling through Ras/IRF4 promoted Tr1 differentiation in vivo." (PMID 34177953, 2021). "Here, gB498–505/Kb, p60217–225/Kd, and LLO91–99/Kd Tet+ CD8+ TM cells underwent the most robust up-regulation of IRF4 expression during challenge infection in the presence of their respective cognate Ag." (PMID 34516896, 2021). "When we looked at different IRFs, we found that Irf7, Irf8, Irf5, and Irf4 were significantly upregulated in WT mouse brains upon infection with JEV." (PMID 34379515, 2021). "The IRF4 protein acts like a switch that turns on and off some genes involved in the body’s response to infection." (PMID 29537367, 2018). "Within upregulated genes, IRF4 is important in the regulation of IFN-γ in response to infection by virus, and in the regulation of interferon-inducible genes." (PMID 29572470, 2018). "Mice with IRF4 deficient CD11c+ cells had less secretion of IL-4, IL-15 and IL-13 after immunization with OVA and papain as well as during infection with the nematode Nippostrongylus brasiliensis." (PMID 29343807, 2018). "Although we were unable to directly confirm protein expression in the latently infected PC, the adoptive transfer data fits into a well-established model in which M2-driven IRF4 expression facilitates PC differentiation during MHV68 infection." (PMID 28767707, 2017). "Following L. monocytogenes-infection, listeria-specific IRF4−/− CD4+ T cells showed impaired TH1 differentiation and failed to expand to the level observed for WT CD4+ T cells." (PMID 27762344, 2016). "Whereas WT CD4+ T cells displayed elevated T-bet expression following infection, IRF4−/− CD4+ T cells presented with expression levels comparable to those of cells from uninfected mice." (PMID 27762344, 2016). "Similar to that seen with acute infections, we find here that the levels of IRF4 also regulate the magnitude of the CD8+ T cell response to LCMV-clone 13 at D8 post infection." (PMID 26714260, 2015).
infection (continued). "We noted massive accruement of pathologic cryptococcal antigen-specific Th2 cells in the lungs following infection that was coordinated by lung-resident CD11b+ IRF4-dependent conventional dendritic cells." (PMID 25764512, 2015). "The data presented above indicated that LCMV-clone 13-infected Irf4+/fl mice have a lower T-bet to Eomes ratio than WT mice in their virus-specific CD8+ T cells at all time points investigated post-infection." (PMID 26714260, 2015). "Relative to WT mice, a lower proportion of Irf4+/fl mice controlled LCMV-clone 13 infection in the kidney, liver and serum when examined more than 100 days p.i.." (PMID 26714260, 2015). "Reduced expression of IRF4 skews this ratio in the favor of Eomes during infection with LCMV-clone 13, resulting in reduced differentiation of T-bet+ Eomes- precursors and impaired viral control." (PMID 26714260, 2015). "On day 14 post-infection, splenocytes were harvested and analyzed for IRF4 levels by intracellular staining coupled with flow cytometry." (PMID 24391506, 2014). "Increased expression of IRF4 and GBP4, which is associated with hypomethylation, could push TI calves towards T cell exhaustion and an inability to appropriately respond to infection." (PMID 40316897, 2025). "Viral latency transcripts were highly enriched in Bla+ data sets of both M2.Stop and WT MHV68, however, only AID+Bla+ samples from WT MHV68 infection showed increased transcription of Il10 and Irf4, which is consistent with previous work demonstrating that M2 upregulates their expression." (PMID 39843898, 2025). "IRF4-deficient mice exhibit reduced NKp46+ ILC3s, expanded precursor-like NKp46−CCR6− ILC3s, and impaired interleukin-22 (IL-22)/IL-17A production, increasing susceptibility to infections." (PMID 40585371, 2025). "Besides MUC19, there are other interesting CNVs shown from our primary infection model, including IRF4/DUSP22 duplication and Notch homolog 2 N-terminal-like protein A (NOTCH2NLA) deletion." (PMID 40996224, 2025). "Dermal CD301b+ cDC2s are distinct from epidermal or CD207+ (Langerin) dermal DC1s, are dependent upon transcription factor interferon regulatory factor 4 (IRF4), and are significant drivers of Th2 cell development and immunity upon infection with Nippostrongylus brasiliensis." (PMID 38932162, 2024). "Additionally, in vivo CRISPR screens in LCMV Arm and chronic Cl13 infection mouse models discovered that Batf and Irf4 cooperate in binding chromatin areas that determine T cell differentiation to Teff." (PMID 38581063, 2024). "Thus, we propose that increased IRF4 expression in T1 LCLs reduces lytic infection not only by attenuating BCR signaling, including NFAT activation, but also by decreasing NFATc1 and NFATc2 expression." (PMID 35472072, 2022). "Reduced IRF4 expression in T2 cluster 9 cells may explain why these cells are much more likely to progress to fully lytic infection (cluster 10) in comparison to T1 cluster 9 cells." (PMID 35472072, 2022). "Irf4−/− mice exhibited significantly reduced survival and increased body weight loss and developed more severe lung pathology compared with Irf4+/− controls, suggesting an important role for IRF4 in protective immunity against pdmH1N1 infection." (PMID 33772013, 2021). "Indeed, the analysis of the transcriptomics of the heart over the time of infection showed increased expression of Irf4 a soon as day 7 of infection, being significantly higher as the disease progressed." (PMID 33395408, 2021). "Follow-up studies, including groups of uninfected control animals, may specifically focus on analysing GBP7 and IRF4 expression at several time points following infection." (PMID 33918448, 2021). "As IRF4 help B-cell development, a genetic mechanism may explain why the lymphocyte subsets in our patients remained unchanged (despite antibiotic, infection by TW remains and induces altered kinds of B cells)." (PMID 30811404, 2019).
infection (continued). "In confirmation of this prediction, we found that the CD8 bTRM stained with tetramers for the dominant DbLT359 MuPyV epitope exhibited higher levels of TCR-signaling, as reflected by the higher expression of IRF4 in the brains than in spleens of mice at 45 days post-infection (dpi)." (PMID 31105690, 2019). "Interestingly, while P14 T cells responding to 35A virus in vivo upregulated IRF4 expression at day 4 post infection, this expression was significantly less than in the response to Clone 13 infection." (PMID 26915099, 2016). "In response to L. monocytogenes infection, we detected reduced accumulation of CD4+ T cells responding to listeria-antigen with the up-regulation of CD40L, and in competitive transfer experiments, IRF4−/− CD4+ T cells were outnumbered by WT CD4+ T cells following infection or peptide immunization." (PMID 27762344, 2016). "Of these, IRF4 expression increased but IRF8 expression decreased during infection." (PMID 25658110, 2015). "Based on previous studies showing that fatality from LCMV-cl13 infection results from excessive T cell responses leading to immunopathology, these data suggest a more robust effector response of WT compared to Irf4+/fl P14 cells to the LCMV-clone 13 infection, consistent with previous observations." (PMID 26714260, 2015). "We propose that during infection, in response to viral reactivation and the transition from germinal center or memory B cell to plasma cell, M1 expression is activated by the synergistic effects of viral Rta and cellular IRF4." (PMID 25101696, 2014). "Additionally, while mouse models were used to characterize IRF4 deficiency, whether these findings translate to human ILC3 biology—particularly in the context of intestinal inflammatory diseases or infections—warrants further validation." (PMID 40585371, 2025). "By day 17 post-infection, the CD19+ B cell population, along with the assayed markers, including CD38, PD-L1, Ki-67, and IRF4 within this population, was significantly higher in PBMCs depleted of CD4+ T cells compared with intact PBMCs." (PMID 40733503, 2025). "Eight days after infection, GFP-Irf4+/fl, GFP+Irf4+/fl, GFP-Irf4-/fl and GFP+Irf4-/fl CD4+ T cells were sorted and analyzed by single cell ATACseq (assay for transposase-accessible chromatin sequencing)." (PMID 40726986, 2025). "Like both SRF and IL-2, the transcription factor IRF4 is dispensable for initial CD8+ T-cell activation and proliferation during infection, but necessary for sustained expansion and SLEC proliferation." (PMID 39261466, 2024). "Interferon regulatory factor 4 (IRF4) is a crucial member of the IRF family of transcription factors and is pivotal in orchestrating the body’s defense against tumors and infections by modulating the differentiation and functionality of immune cells." (PMID 39609883, 2024). "While IL-6, IRF4, IRF6, and CXCL2 were significantly unchanged, TNF-α was significantly elevated in the infection-derived EVs at both 48 h and 72 h when compared to the control-derived EVs (* p = 0.01 and * p = 0.02, respectively) (respectively)." (PMID 36979955, 2023). "Irf4-/- mice showed reduced accumulation of CD4+ T cells in the colon, both under homeostatic conditions and after infections." (PMID 37469513, 2023). "Further studies, including groups of uninfected control animals, should particularly focus on the expressions of GBP7, RFK, IRF4, and EPHA3 at several time points following infection." (PMID 33918448, 2021). "During infection, IRF-8 is induced in antigen presenting cells (APC) by IFN-γ and TLR ligands, binds to IRF-4, and stimulates IL-12 as well as IL-18 secretion, resulting in CD4+ Th1 cell differentiation and elimination of intracellular pathogens." (PMID 28968468, 2017). "Conversely, rapamycin treatment reduced mTOR signaling and impaired IRF4 expression and CD8+ T cell differentiation, leading to impaired viral clearance and host recovery from infection." (PMID 27242787, 2016).
infection (continued). "In contrast, the transcription factor interferon regulatory factor 4 (IRF4) was critical for proliferation and survival of CD8+ T cells responding to infection with influenza virus and L. monocytogenes." (PMID 27242787, 2016). "Further, high levels of IRF4 are required for robust expansion of virus-specific T-bet+ Eomes- effector CD8+ T cells and viral control at early times post-infection." (PMID 26714260, 2015). "In general, DCs were more responsive than Mφs to infection, with more genes induced, such as SOCS2, ISG20, TRAF5 and IRF4." (PMID 18167562, 2008). "The IRF4 level remained relatively high in CD19+ B cells during the establishment of lymphoblastoid cell lines (LCLs) but gradually declined in CD4+ T cells and remained at a low level until CD4+ T cells disappeared approximately two weeks post-infection." (PMID 40733503, 2025). "Induced Irf4 deletion after infection did not further reduce the frequencies of IL-4+, IL-13+ or IL-17A+ T cells indicating that IRF4 is not essential for production of these cytokines in Th2 and Th17 memory cells." (PMID 37469513, 2023). "Following infection with C. rodentium or S. ratti, Irf4-/- mice failed to control infection, resulting in systemic dissemination of C. rodentium and delayed clearance of S. ratti, respectively." (PMID 37469513, 2023). "While a few of these genes are easily identifiable for involvement in antiviral or inflammatory responses, such as interferon regulatory factor 4 (IRF 4) or TGF beta, a further investigation shows that several of the transcripts do, in fact, play a role in responses to infection." (PMID 32526950, 2020). "Antiviral activity towards PRRSV and the IBV/PRRSV coinfection displayed upregulation of interferon regulatory factors (IRFs) that included IRF1, IRF4, IRF8, expressed in the PRRSV infection and IRF7 showing up in place of IRF1 in the coinfection in this study." (PMID 33187194, 2020). "Through its IRF-8 association domain (IAD), IRF-8 interacts with other transcription factors, such as PU-1, IRF-1, IRF-4, and IRF-2, and plays an important role in immunity against tumors and infections with intracellular pathogens, including bacteria, viruses, and protozoan parasites." (PMID 28968468, 2017). "As a control for RUNX3, CBFβ and IRF4 depletion experiments, EBNA2 ChIPs were performed in a similar manner, on the same batch of chromatin, after their infection with each shRNA-expressing lentivirus to show that the trend of reduced EBNA3 enrichment after knock-down was specific." (PMID 27903901, 2017). "Reduced IRF4 expression results in skewing of this ratio in the favor of Eomes, leading to lower proportions and numbers of T-bet+ Eomes- precursors and poor control of LCMV-clone 13 infection." (PMID 26714260, 2015). "Here we find that IRF4 joins this group of transcription factors, as reduced expression of IRF4 leads to persistence of LCMV-clone 13 infection, but does not affect clearance of LCMV Armstrong." (PMID 26714260, 2015). "Beginning at D10 p.i., we observed that a proportion of recipients receiving WT P14 cells were succumbing to the infection, a response not seen in recipients that received P14 Irf4+/fl cells." (PMID 26714260, 2015). "While IRF4 and STAT6 had similarly elevated expressions at 2, 4, 8 and 12 weeks, JAK1 and NFATC4 were upregulated at comparable levels from 2 to 8 weeks and then downregulated at 12 weeks post-infection." (PMID 23448601, 2013). "In addition, except for 4 of the regulatory genes (IRF4, JAK1, NFATC4 and STAT6), many of the other genes in this pathway were only transiently expressed at 2 (IL4R and PTPRC) or 4 and/or 8 (IL13, IL4 and CEBPB) weeks post-infection." (PMID 23448601, 2013).
infection (continued). "Together with the finding that the GM-CSF-induced expression of IRF4 could be inhibited by LXR agonists, our data indicate that DEX treatment can trigger a profound immunosuppressive effect in the Scd1+ and Fos+ resident AMs, which further disrupted the anti-infection immunity of the hosts." (PMID 37359523, 2023). "The analysis over time of Irf4 expression in peripheral blood of B. burgdorferi–infected mice showed a slight reduction at the initial phases (week 1 of infection) that increased over time, being significantly higher than in noninfected controls at week 8 of infection." (PMID 33395408, 2021). "Although IRF4 and IRF8 are also expressed in DCs, Syk expression was not affected by infection of IRF4 or IRF8 (data not shown), demonstrating that monomeric PU.1 transactivates the Syk gene in DCs in the same manner as that in MCs." (PMID 29386516, 2018). "Western blot analysis showed up-regulation of IRF4 but no observed change in IRF8 protein level after 0, 2, 4, 7 and 15 days of post-infection." (PMID 23658517, 2013). "When the data from the WT mice were segregated according to viral titers, we found that WT mice that had not controlled LCMV-clone 13 infection at this time point, appeared as outliers and had proportions and numbers of T-bet+ Eomes- virus-specific CD8+ T cells comparable to Irf4+/fl mice." (PMID 26714260, 2015). "Consistently, the RT-qPCR results show that LMP1, IRF4, and PD-L1 were all significantly higher in PBMCs without CD4+ T cells 17 days post-infection, and proliferating colonies were significantly more grown from PBMCs depleted of CD4 T cells compared with intact PBMCs by day 26 post-infection." (PMID 40733503, 2025). "The down-regulation of genes involved in the interferon response (i.e. irf1, irf4 or irf8) in infected samples at 7 dpi (and lack of up-regulation of other interferon genes at this time point) suggests that ISAV modulates this process as part of its infection and replication strategy." (PMID 33985436, 2021).